RNU6-300P (RNA, U6 small nuclear 300, pseudogene)
Gene: Small nuclear RNA gene on chromosome 6 (151,201,341 to 151,201,444, forward strand). Ensembl gene ENSG00000238616.
Homologues: Orthologues: chimpanzee U6 (97% identical), macaque U6 (96% identical), rat LOC120096097 (68% identical), mouse Gm23341 (61% identical), mouse Gm24129 (54% identical). Paralogues in human: RNU6-196P (82% identical), RNU6-211P (82% identical), RNU6-1152P (81% identical), RNU6-393P (81% identical), RNU6-434P (81% identical), RNU6-836P (81% identical), RNU6-1145P (80% identical), RNU6-1316P (80% identical), RNU6-144P (80% identical), RNU6-16P (80% identical), RNU6-20P (80% identical), RNU6-214P (80% identical), and 1285 more.